MUC1 (mucin 1, cell surface associated)
Diseases named in the same sentence as MUC1 in open-access papers (continued):
Sharing a sentence is not in itself a finding about the gene and the disease.
tumor (continued). "Consequently, increased MUC1 expression and sialylation are expected to enhance KL-6 detection in tumor cells." (PMID 41416421, 2026). "However, during tumor growth, MUC1 becomes overexpressed due to changes in glycosylation, which induces chronic inflammation and malignant transformation, promoting cancer progression." (PMID 40312353, 2025). "The authors suggested that αGlcNAc acts as a tumor suppressor by inhibiting MUC1 signaling." (PMID 41154387, 2025). "We have shown an ambiguous trend in changes in the concentration of CA19-9, which does not coincide with changes in other tumor markers associated with MUC1." (PMID 40699615, 2025). "Among recognized tumor antigens, mucin-1 (MUC1) remains one of the most prevalent targets." (PMID 40284463, 2025). "Additionally, MUC1 expression was notably higher in CRC tumour tissues, a well-studied marker for poor prognosis." (PMID 40348885, 2025). "However, a therapeutic MUC1 DNA vaccine, pcDNA3.1-MUC1 (20 μg, delivered by gene gun and electroporation), elicited enhanced anti-tumor responses in the murine colorectal model." (PMID 41012179, 2025). "MUC1@ACS NPs accumulation at the tumor site was 6.02 times greater than that of free drug." (PMID 40689201, 2025). "For example, the first-generation vaccinestargeted shared tumor-associated antigens (e.g., NY-ESO-1, MAGE, CEA,MUC1), but results suggest focusing onpatient-specific neoantigens may be more effective." (PMID 41124104, 2025). "Similarly, mice receiving 100 μg of a chimeric MUC1 DNA vaccine, encoding the transmembrane- and C-terminal domain-deleted Muc1 gene fused to the human HSP70 gene, had greater anti-tumor effects." (PMID 41012179, 2025). "MUC1 stimulates tumor invasion via the attenuation of E-cadherin." (PMID 41154387, 2025). "Moreover, interacting with HIF-1, MUC1 induces a metabolic reprogramming responsible for gemcitabine chemoresistance and hypoxic tumor microenvironment." (PMID 40001578, 2025). "Prior research has suggested that the weak natural immune response to MUC-1 may result from the inefficient processing of tumor MUC1 protein by APCs, leading to the insufficient activation of MUC-1-specific helper T cells." (PMID 40723238, 2025). "Furthermore, Tn antigens on MUC1 are recognized by MGLs on macrophages and DCs, playing a critical role in tumor progression." (PMID 41383589, 2025). "Mucin 1 (Muc1) is a tumor-specific antigen that is overexpressed in several adenocarcinomas." (PMID 39911383, 2025). "In addition, flow cytometric analysis showed increased infiltration of CD8+ T cells into the tumor microenvironment after treatment with either the MUC1 mRNA vaccine or CTLA-4 siRNA-loaded NLE, with the combination therapy showing the strongest effect." (PMID 40943370, 2025). "The tumor marker cancer antigen (CA) 27.29 is one way to measure MUC1." (PMID 40924700, 2025). "Notably, a study has revealed that higher expression of MUC1 can potentiate the tumor-promoting functions of TGF-β." (PMID 40655139, 2025). "MUC1 glycan isomerization has been implicated in altering EGFR recycling and promoting immune evasion, thereby contributing to the development of a drug-resistant tumor microenvironment." (PMID 41020875, 2025). "For instance, high levels of MUC1 may suppress cytotoxic T cell activity, thereby aiding tumor escape from immune surveillance." (PMID 40655139, 2025). "Although MUC1 3Adj C3-liposome females generated a strong T-cell and IgG response, their significantly larger tumor size suggests this immune response was ineffective at controlling tumor growth." (PMID 40284463, 2025). "In vivo, MUC1 knockdown cells showed reduced tumor growth in SCID mice." (PMID 40699746, 2025). "In GC, the presence of the altered glycosylation of MUC1 in tumor microenvironment pathway (WP4480) (BH = 2.82E-04), linked to the tumor microenvironment is clearly related to the pathology with 7 genes and the EPO receptor signaling pathway (WP581) (BH = 2.82E-04), with 14 genes." (PMID 40920362, 2025).
tumor (continued). "However, in cancer cells, abnormal glycosylation and the increased expression of MUC1 often leads to processes like tumor invasion, generalized spread to parts of the body, the formation of blood vessels, and apoptosis." (PMID 40699746, 2025). "Our results demonstrated that the MUC1 C3-liposome vaccine could effectively hinder tumor growth and induce robust antibody and T-cell immune responses against MUC1-positive tumor cells." (PMID 40284463, 2025). "The MUC1 gene is overexpressed in malignant breast tumors, allowing the use of the gene product CA 15-3 as a tumor marker for BC, and the serum level of CA 15-3 corresponds to the tumor size." (PMID 40710097, 2025). "The presence of human MUC1 has been shown to induce Type I macrophages in mouse models of colitis-associated cancer (CAC), highlighting MUC1's inflammatory role and its involvement in tumor promotion and progression." (PMID 40443562, 2025). "-PSCA-CAR-T delayed tumor progression;-MUC1-CAR-T ineffective in PDX models." (PMID 40904467, 2025). "The aim of our study was to evaluate whether delivery of MUC1 100mer peptide and TLR agonists with C3-liposomes would effectively protect mice against a tumor challenge using MUC1-expressing tumor cells." (PMID 40284463, 2025). "One explanation may be the higher MUC1 expression observed in pancreatobiliary and invasive cases, which can activate the interferon‐gamma signaling pathway in tumor cells, potentially leading to increased caspase‐1 expression." (PMID 39969214, 2025). "Moreover, antitumor vaccinations, based on MUC1 glycosylated tricomponents, clearly reduced the tumor burden by stimulating humoral and cellular immune responses." (PMID 40001578, 2025). "To understand why sex differences in tumor growth were observed, particularly in female mice vaccinated with MUC1 3Adj C3-liposomes, we evaluated the spleen cells for the presence of monocytic MDSCs (CD11b+Ly6C+) and granulocytic MDSCs (CD11b+Ly6G+) with flow cytometry." (PMID 40284463, 2025). "Additionally, the three tumor markers CA-125, MUC1, and CEA are seen as complementary in the diagnosis of primary metastases." (PMID 40385462, 2025). "Transfection of MUC‐1 with siRNA targeting Wee1 resulted in a strong reduction in cell proliferation and an increase in apoptosis, consistent with the finding that dysregulated Wee1 function has a role in tumour progression." (PMID 39528354, 2025). "The increased presence of MDSCs in the female MUC1 3Adj C3-liposome group could result in systemic immune suppression and is a possible explanation for the significant difference in tumor growth between female and male mice in this vaccine group." (PMID 40284463, 2025). "Therefore, kaempferol’s effect on the JAK/STAT pathway, as well as its inhibitory effects on MUC-1 and NF-κB1 expressions, indicates the potential of this compound to reverse the reduced tumor infiltration of T cells in the TIME." (PMID 41463161, 2025). "Given that metaphase effectors influence cell division patterns, which are critical for CSC expansion, we hypothesized that MUC1 may be involved in the enrichment of tumor spheroidal cells in SCLC." (PMID 40349179, 2025). "SIGLEC9+CD4+T-cells infiltrated around the tumor nests, and MUC1 was expressed in the tumor nests." (PMID 41418390, 2025). "In accordance, we detected enhanced c-Jun stainings in MUC-1 tumor spheroids." (PMID 41310103, 2025). "With the purpose to evaluate the specific contribution of IGF1R and IR in mediating ACC cell proliferation, we performed in vitro experiments with four different cell lines: H295R and JIL-2266, derived from ACC primary tumours, and MUC-1 and TVBF-7 derived from ACC metastatic tissues." (PMID 40038716, 2025). "MUC1, with its aberrant expression in cancer, can enhance the tumor-promoting aspects of TGF-β." (PMID 40655139, 2025). "MUC1 expression was also upregulated in tumor areas, which may play a role in the malignant phenotype of cancer in this region." (PMID 41187747, 2025).
tumor (continued). "We confirmed that this was not due to antigen loss by evaluating PSCA and MUC1 surface levels on outgrowing tumor cells (on day 20), which demonstrated expression of both antigens comparable to the untreated condition." (PMID 40808942, 2025). "For instance, Deng's research indicated that miR‐206 could directly interact with the 3′ untranslated region (3′UTR) of the MUC1 gene, suppress its expression and exert effective anti‐tumour activity by inhibiting MUC1 expression." (PMID 40521987, 2025). "Interestingly, female mice vaccinated with MUC1 3Adj C3-liposomes followed a similar pattern and produced more IFN-γ-producing T cells than free MUC1 and 3Adj C3-liposomes groups, despite the significantly increased tumor growth." (PMID 40284463, 2025). "Interestingly in MUC-1, Wnt5A protein hotspots were often localized at the periphery of the tumor spheroid, which furthermore showed signs of potential budding or localized close to highly open chromatin." (PMID 41310103, 2025). "MUC1 glycoprotein (Mucin 1, also known as MUC1), a large transmembrane glycoprotein is often abnormally increased, and its glycosylation pattern is also altered, leading to the formation of tumor-associated glycoantigens." (PMID 39861694, 2025). "Additionally, markers related to their role in immune evasion and tumour invasiveness, such as MUC1, and markers confirming epithelial origin, such as cytokeratins, have gained importance in understanding tumour invasion and metastasis." (PMID 40144054, 2025). "Although MUC1 as a transmembrane glycoprotein is typically expressed in the cell membrane of healthy tissue, during malignant transformation it can be overexpressed both on the cell surface and within the cytoplasm of tumour cells." (PMID 40144054, 2025). "In cancer cells, MUC1 supports tumor progression by promoting resistance to apoptosis." (PMID 39796763, 2025). "Tn antigen-modified vaccines significantly inhibited tumor growth in MUC1 transgenic mice.Self-adjuvant glycopeptide vaccines (MUC1-Tn-Pam3CSK4) enhance immune responses via TLR2 agonists, inducing robust humoral and cellular immunity in tumor-bearing mice without the need for exogenous adjuvants." (PMID 40655139, 2025). "CK20 levels were correlated to MUC1 levels as well as to tumor size." (PMID 38324850, 2024). "For instance, α2,3-sialylated MUC1 was reported to bind macrophage receptor, sialoadhesin (Siglec-1), and so may be involved in recruiting macrophages into the tumor site." (PMID 38611013, 2024). "Moreover, co‐culture results also showed that polarisation of macrophages was mediated by MUC1 expressed by tumour cells." (PMID 38778448, 2024). "The success and broader application of personalized immunotherapies have been limited due to the heterogeneity in production, secretion, and glycosylation patterns of MUC1 and the distribution of Siglecs receptors among various tumor types and between patients." (PMID 38611013, 2024). "Furthermore, MUC1+ tumour cells showed enhanced pathway activities in lipid metabolism and TGF‐β production." (PMID 39422697, 2024). "It has been demonstrated that MUC1 overexpression in epithelial tumor cells is essential to the transformation process, but little is known about MUC1′s function in immune cells throughout the development of cancer and in regulating the interaction between tumor cells and the immune system." (PMID 38540735, 2024). "Therefore, MUC1 is expected to become a novel marker indicating tumor progression, holding significant value in clinical diagnosis, treatment and prognosis assessment of cancer." (PMID 39491020, 2024). "Furthermore, as MUC1 is a cell surface tumor antigen, MUC1 antibodies can target tumor cells for destruction by antibody-mediated cellular cytotoxicity (ADCC) and antibody-mediated phagocytosis (ADCP)." (PMID 39450169, 2024).
tumor (continued). "Additionally, studies have shown that MUC1 is elevated in different types of tumor tissues including breast cancer, ovarian cancer, lung cancer, and colorectal cancer." (PMID 38933439, 2024). "As EGFR and MUC1 were stained in consecutive sections with a thickness of 4 μm, which was smaller than the averaged diameter of tumor cells (7-20 μm in most cases), we could observe if they were co-expressed in the same tumor cells." (PMID 39664199, 2024). "More recent studies have investigated the role of MUC1 in the mechanisms of tumor immune evasion." (PMID 38540735, 2024). "Highly O-glycosylated epidermal MUC1 is a marker for monitoring tumor recurrence." (PMID 39491020, 2024). "Furthermore, enhanced antibody-dependent tumor cell cytotoxicity by neutrophils was achieved by targeting the Siglec–sialylated MUC1 immune axis, either by blocking Siglec-9 or by reducing tumor cell sialylation." (PMID 38611013, 2024). "Our data support that GT-00AxIL15 specifically binds the glycosylated but not the non-glycosylated MUC1 peptide with high affinity, confirming glycan-dependency as hallmark of tumor-selective MUC1 binding." (PMID 38338686, 2024). "In tumor immune microenvironment research, the roles of MUC1 and MUC16 in regulating mechanisms by which tumor cells evade immune surveillance, and how these proteins influence immune escape and treatment response through different pathways, are currently focal points of investigation." (PMID 38361923, 2024). "Therefore, we first aimed to study the pharmacodynamics of a STAT3-inhibitor Napabucasin in low vs high MUC1 tumor cells in vitro." (PMID 38326371, 2024). "A preclinical study showed that MUC28z CAR-T cells, designed to target MUC1, were effective in recognizing and attacking MUC1-positive tumors in mice, significantly reducing tumor size within four days with a prolonged ability to attack cancer cells for up to 81 days after treatment." (PMID 39759220, 2024). "The hypoglycosylated tumor form of MUC1 is found on many adenocarcinomas, including those of the breast, prostate, lung, ovaries, pancreas, colon, and stomach, as well as certain hematopoietic malignancies such as T and B cell lymphomas, leukemias, and multiple myelomas." (PMID 39449327, 2024). "One notable example involves MUC1, a glycoprotein commonly overexpressed in various tumor tissues." (PMID 40808797, 2024). "Tumor cells showed a cytoplasmic positive reaction for MUC1 in both cases." (PMID 38592620, 2024). "Since STAT3-MUC1 signaling is constitutively active in high-MUC1 tumor cells, we hypothesized that high-MUC1 cells are more sensitive to STAT3-inhibition." (PMID 38326371, 2024). "In this study, we further characterize 12 of these antibodies for binding to MUC1 on target cells and fully elucidate the mechanisms of action by which 3 of these antibodies might eliminate or facilitate elimination of tumor cells." (PMID 39449327, 2024). "Microvesicles derived from tumors, carrying the MUC1 tumor glycoantigen, could be utilized to pulse DCs and activate an IFN-γ response mediated by MUC1-specific CD8+ T cells, ultimately promoting an antitumor response." (PMID 38562940, 2024). "Studies have shown that tumour‐related MUC1 glycosylation is closely related to DC recognition." (PMID 39400935, 2024). "Furthermore, macrophages are significantly activated by the binding of CD169 to sialylated MUC1, thereby interfering with cancer immune surveillance and ultimately promoting tumor growth." (PMID 38248854, 2024). "MUC1 is a transmembrane mucin glycoprotein expressed in tumour cells, and it is also a well‐established multifaceted oncoprotein with a critical role in tumorigenesis and may serve as a potential target for cancer vaccines." (PMID 38778448, 2024). "The adapter protein coded by the virus helps T cells recognize MUC1-positive tumor cells." (PMID 38910324, 2024). "TA MUC1 is one of the key carriers of the glycocode in tumor cells." (PMID 38611013, 2024).
tumor (continued). "Instead, the role of the BsTe is to recruit and activate T cells against MUC1-positive tumor cells." (PMID 38910324, 2024). "Finally, the resulting CD8+ T-cells can recognize and kill murine EL4 tumor cells expressing the Tn antigen bound to its biological substrate MUC1." (PMID 39772036, 2024). "We observed that CD56 and/or CD16-positive NK cells could be effortlessly identified in the interface area between cancer cell clusters and the cancer cell lysis site in the MUC1-expressing xenograft tumor tissue." (PMID 38390321, 2024). "In light of these findings, there is abundant potential for tumor therapies targeting MUC1." (PMID 37666495, 2024). "Additionally, we performed immunohistochemical staining using an anti-human CD56 antibody on tumor tissue sections, confirming the accumulation of infiltrated MUC1-NK cells within the MUC1-positive tumors." (PMID 38390321, 2024). "The superior performance of CA 15–3 in predictive modeling, particularly with the ANN approach, suggests that CA 15–3 may possess more detectable or relevant characteristics to tumor progression stages than MUC-1." (PMID 39031228, 2024). "We performed immunohistochemical staining for MUC1 in tumor tissues taken by endoscopic biopsy." (PMID 38592620, 2024). "Furthermore, vaccination with Qβ-MUC1-TF provided significant protection against cancer cells in a model of tumor metastasis." (PMID 39591192, 2024). "As an oncogenic driver, MUC1 increases the aggressiveness, metastatic potential, and drug resistance of cancer by promoting tumor cell proliferation, EMT, and epigenetic changes, and facilitates immune evasion through interactions with immune cells in the tumor microenvironment." (PMID 38361923, 2024). "In addition, by coupling tumor-related MUC1 glycopeptides and T-helper-cell epitopes with polymer-carriers, the immunogenicity of anti-tumor vaccines can be enhanced." (PMID 38668222, 2024). "For example, MUC1/CA153 could promote tumor invasion when expressed in its highly-glycosylated isoform." (PMID 38778252, 2024). "Targeting tumor MUC1 glycoprotein inhibited the growth of TNBC, among others." (PMID 38329441, 2024). "When TILT-322 kills MUC1-positive tumor cells, MUC1 expression is reduced." (PMID 38910324, 2024). "Muc1-Bi antibodies recruit NK cells to drive effective and specific cell killing of MUC1-overexpressed tumor cells.Therefore, we hypothesized that bifocal antibodies targeting both MUC16 and CD16 would have similar effects in tumors." (PMID 38758220, 2024). "Furthermore, the transcriptional regulatory sequence of MUC1 facilitates the selective expression of target genes in MUC1-positive tumor cells." (PMID 39886667, 2024). "In this scenario, it has been shown that MUC1 can promote cancer stemness and could be used to identify circulating stem cell-like tumor cells." (PMID 38540735, 2024). "Thus far, the immune-modifying function of a CTLA4 inhibitor combined with an MUC1 mRNA nanovaccine in the tumor microenvironment (TME) of triple-negative breast cancer (TNBC) has been evaluated by examining the cytotoxic immune cells and cytokines." (PMID 38397971, 2024). "Similarly, the possibility of crosstalk between tumour and macrophage spots was assessed by the expression signature of the MUC1 and MS4A4A genes." (PMID 38778448, 2024). "Although the exact role of MUC1 in tumor progression is unknown, there is evidence to suggest that it may play a role in several oncogenic pathways, including cell adhesion, differentiation, apoptosis, proliferation, and angiogenesis." (PMID 38540735, 2024). "Moreover, MUC1 is involved in the biological processes of tumor cells by regulating proliferation, epithelial–mesenchymal transition, and epigenetics, thus playing a significant role in the occurrence and development of tumors." (PMID 39491020, 2024).